VN1R3 (vomeronasal 1 receptor 3)
Description:
Putative pheromone receptor.
Synonyms: V1RL3; FKSG46
Gene: Unprocessed pseudogene on chromosome 16 (31,807,926 to 31,808,844, reverse strand). Ensembl gene ENSG00000180663.
Subcellular location: Cell membrane